MET (MET proto-oncogene, receptor tyrosine kinase)
Diseases named in the same sentence as MET in open-access papers (continued):
Sharing a sentence is not in itself a finding about the gene and the disease.
cancer (continued). "HGF/MET aberrant activation plays important roles in the development and progression of several human cancers including lung, renal, gastrointestinal, thyroid, and breast carcinomas, as well as sarcomas and malignancies of the nervous system such as GBM among others." (PMID 35626056, 2022). "To determine whether such differences exist, we compared the status of known MET effector pathways in METΔex14-expressing cancer lines (Hs746T and H596) to another MET-addicted line with high-level amplification of the wild type MET gene (H1993)." (PMID 35326531, 2022). "As a whole, our results point to KRAS being the crucial signaling effector that is responsible for facilitating MET-driven growth in METΔexon14-addicted cells, while also playing a role in maintaining growth and tumourigenesis in MET WT-addicted cancer cells as well." (PMID 35326531, 2022). "Therefore, the use of MET immunoreactivity to facilitate the stratification of cancer patients into treatment categories is still a subject of debate." (PMID 35326642, 2022). "To investigate this hypothesis, we generated cancer lines conditionally expressing oncogenic forms of MET effectors KRAS, PI3K, and STAT3 (p20-KRASG12D, p20-PIK3CAE545A, and p20-STAT3A662C_N664C)." (PMID 35326531, 2022). "The expression of MET and phosphorylated MET has been studied in cancers." (PMID 35301291, 2022). "Crucially, this observation was made by comparing the transcriptional profiles of MET-addicted cancers expressing either METΔexon14 or exhibiting high-grade amplification of the wild type MET gene, suggesting divergent mechanisms underpinning MET-driven tumourigenesis." (PMID 35326531, 2022). "MET (Mesenchymal-epithelial transition factor) is a receptor tyrosine kinase that is proposed as a promising target in cancer therapy due to the predominant oncogenic signaling cascades that has been shown crucial to malignant progression and tumorigenesis of several cancer types." (PMID 35941699, 2022). "It has been shown that the E5 oncoprotein may play a key role in HPV-induced cancers, especially in the metastatic process, by upregulating the expression of MET transcripts and the hepatocyte growth factor receptor (HGFR)." (PMID 35163748, 2022). "HGF released by cancer and stromal cells impacts the development of cancer cells, promotes cancer cell proliferation and survival and stimulates metastatic dissemination via activating the signaling pathway of its receptor, c-MET." (PMID 35630066, 2022). "We have recently reported that in specific MET-overexpressing cell models, MET inhibition (METi) largely affects numerous phosphorylation circuits in cancer cells and regulates also cellular response to ionizing radiation (IR) by modulating multiple key effectors of the DDR machinery." (PMID 36494469, 2022). "This retrospective review of NSCLC genomics data from the BC Cancer Genomic Lab Oncopanel Dataset summarizes the frequency of actionable driver mutations (EGFR, KRAS G12C, MET Exon 14 skip, ALK fusion, and ROS1 fusion), PDL-1 expression, and treatment wait times among five health authorities." (PMID 36661661, 2022). "Drugs that target c-MET may offer a new strategy for the control of aggressive cancers and the combination of HGF/MET inhibitors with conventional chemotherapy in patients affected by different cancer types has shown promising results." (PMID 35480115, 2022). "Hsa_circ_0082003, one of circRNAs derived from MET gene, promotes the progression of cancer by sponging miR-145-5p in non-small-cell lung cancer, and circMET (also known as hsa_circ_0082002) induces hepatocellular carcinoma development and immune tolerance via miR-30-5p." (PMID 35042525, 2022). "ILEI is less well understood than c-MET, but its role in cancer progression is starting to emerge." (PMID 33596971, 2021).
cancer (continued). "The pleiotrophic role of the receptor tyrosine kinase (RTK) c-MET in cellular processes and its important role for cancer progression suggest that c-MET may be a promising target for anticancer therapy." (PMID 33919702, 2021). "c-MET, a kinase receptor for Hepatocyte growth factor (HGF), drives tumorigenesis repressing the Raf kinase inhibitory protein (RKIP), whose loss has been reported in many cancer types overexpressing c-MET, including 50% of CRC." (PMID 34768901, 2021). "The evidence may introduce such small inhibitors as potential therapeutic agents for repressing MET activity and inhibiting cancer cell proliferation and migration." (PMID 34217156, 2021). "Genetic alterations of c-MET and EGFR were previously identified and implicated in the progression of several cancers and were also implicated in the resistance of most cancers to any generation of EGFR-TKIs including the latest third-generation series." (PMID 34512327, 2021). "In a variety of malignant tumors, the MET gene represents one of the drivers of tumorigenesis due to genetic aberrations, including germline or somatic point mutations, splice-site mutations leading to the skipping of exon 14 (MET exon 14 skipping) or gene amplification." (PMID 34638507, 2021). "The antitumor effect of several anti-MET agents with proven efficacy in other cancers may be assessed in CRCs with MET amplification." (PMID 33753878, 2021). "Furthermore, we detected 143 variants in 66 cancer-associated genes, including BMP5, with the highest predicted deleteriousness score of 22.7, MET and USP44." (PMID 34069790, 2021). "Moreover, we found that the specific c-MET inhibitor SU11274 at higher concentration efficiently decreased cancer cell proliferation in both PE/CA-PJ41 and PJ15 cells." (PMID 34257586, 2021). "The MET-signaling pathway has been contributed to the development of several cancers." (PMID 34217156, 2021). "In this respect, the level of MET-GCNG/GA in cancer cells may have importance for the intensity by which this event perturbs the MET-signaling pathway through protein overexpression and prolonged kinase activity." (PMID 34884673, 2021). "Future work will show whether constructing a human bivalent and/or monovalent one-armed IgG1 RDO24 antibody may be effective to create an inhibitory anti-MET antibody for cancer therapy." (PMID 34925346, 2021). "Targeting the MET signaling pathway is an effective strategy in numerous cancer types." (PMID 35693217, 2021). "Therefore, MET-signaling inhibition can be potentially considered as a therapeutic modality for the treatment of different MET-activated human cancers." (PMID 34217156, 2021). "As c-MET activation leads to increased proliferation and growth of cancer cells, it is possible that this type of growth factor receptor gene amplification will be of benefit during selection of stable cancer cell lines." (PMID 33596971, 2021). "Previous studies suggest that some MET cleavage is closely related to cancer." (PMID 33947097, 2021). "In addition, MET is a known favorable interacting partner in cancer, and evidence indicates that MET induces resistance to anti-EGFR drugs in NSCLC28." (PMID 33603128, 2021). "HSF1 inhibition by using HSF1 shRNAs or KRIBB11 decreased the expression of HSF1 downstream proteins, such as HSP70 and HSP27, and also decreased the expression of HSP90/HSP70/BAG3 client proteins, such as BCL2, MCL1, EGFR, MET, and AXL, causing apoptosis of EGFR-TKI-resistant cancer cells." (PMID 34203709, 2021). "Therefore, MET serves as a promising target in the treatment of cancer, as well as a prognostic marker of clinical value." (PMID 34956177, 2021).
cancer (continued). "The major biological themes with these pathways included extracellular matrix organization, cell communication, transport of small molecules, protein metabolism, signal transduction pathways such as MET, rho GTPase, and others that are increasingly recognized in cancer biology." (PMID 34901014, 2021). "We found that HGF/c-MET and immune regulation levels are highly specific in different cancers." (PMID 34261467, 2021). "Moreover, neutrophil expression of thrombospondin 1, IL-1β and the receptor tyrosine-protein kinase MET limit the formation of metastases by blocking the cancer cell mesenchymal-to-epithelial transition and releasing NO individually." (PMID 34674757, 2021). "Thus, our mechanistic studies on NSCLC cell lines with MET amplification are of direct clinical relevance to many cancer types." (PMID 33596971, 2021). "Combination with MET Inhibitors (METis)); thus, it is important to investigate the mechanisms of action of both intrinsic and acquired resistance to enrich our strategies to fight cancers." (PMID 34207383, 2021). "Moreover, the aberrant expression of MET and its ligand, HGF, is associated with poor prognosis and drug resistance in cancers." (PMID 34761497, 2021). "Of note, while MET is often amplified in cancer cells, H1703 cells harbor normal MET copy number." (PMID 34590584, 2021). "String functional protein network analysis revealed an intricate interplay between some of these proteins and MET, which were grouped into pathways highly involved in cancer progression, angiogenesis, invasion/migration, evasion of apoptosis, stem cell self-renewal, and therapeutic resistance." (PMID 34055785, 2021). "In addition to distinguishing between tumors and normal samples, we also attempted to compare the relationship between HGF/c-MET, immune infiltration and survival outcomes in patients with cancer." (PMID 34261467, 2021). "MET is a tyrosine kinase receptor involving invasive growth functioning both in the physiological process during embryogenesis and pathological actions during cancer progression." (PMID 34880333, 2021). "However, hyperactivity of c-MET is evident in a wide range of cancers where it can drive proliferation, survival, motility, and invasion." (PMID 33596971, 2021). "Furthermore, MET inhibition reduces the viability of chemoresistant cancer cells and can synergise with chemotherapy." (PMID 33526881, 2021). "Finally, to further confirm the critical role of SEs in maintaining cancer stemness and promoting metastatic ability, we performed rescue experiments by overexpressing MET in SCC1 cells." (PMID 34172737, 2021). "High c-MET levels often correlate with poor cancer prognosis." (PMID 33596971, 2021). "Conversely, in ovarian and gastric cancer cell lines that display basal MET phosphorylation, MET inhibition with capmatinib or PHA-665752, in combination with paclitaxel or adriamycin, has been shown to lead to accumulation of DSBs compared to chemotherapy alone." (PMID 33526881, 2021). "Moreover, an autocrine loop of MET activation has been reported in several chemoresistant cancer cell lines, leading to their increased viability." (PMID 33526881, 2021). "In particular, high levels of c-MET often correlate with poor prognosis in cancer patients." (PMID 33596971, 2021). "All these data show that MET amplification has broad relevance in many cancers and our study indicates that FAM3C co-amplification may play a comparably important role in all these different cancer types." (PMID 33596971, 2021). "With regard to RTKs, how MET is expressed in MM and whether it could represent a target for this cancer type remains to be further elucidated." (PMID 34884673, 2021). "Similarly, in FGFR2-positive GC, resistance to AZD4547 was abolished by EGFR, HER3, or MET inhibition, indicating that these other RTKs are responsible for cancer cell resistance to FGFR inhibition." (PMID 34830951, 2021).
cancer (continued). "The HGF/MET axis is involved in a series of biological responses, such as proliferation, angiogenesis, migration, invasion, metastasis, and survival, thus contributing to tumorigenesis, development, and progression in different human cancer types." (PMID 34956177, 2021). "This distinction is critical for selecting a patient population in which MET amp drives cancer and may therefore be a target population for treatment with MET inhibitors." (PMID 34677235, 2021). "However, some c-MET inhibitors have been proved to serve as an effective therapeutic option for certain cancers." (PMID 34804015, 2021). "Although significant (p < 0.05), this difference suggests that MMs harbor fairly modest increases of MET-GCN as compared to other cancer types such as NSCLC, in which de novo high-level MET-amplification, often with more than 15 MET gene copies (“gene clusters”), can be detected by FISH analysis." (PMID 34884673, 2021). "In order to reveal the action mechanism by which compound 4 induces a much better inhibitory effect on cancer cell proliferation than cabozantinib, we examined whether two compounds possess differential activity to suppress c-MET expression." (PMID 34575841, 2021). "MET, as a cancer therapeutic target, functions as an oncogene." (PMID 34217156, 2021). "Moreover, the kinase inhibitor crizotinib was specifically designed to inhibit ALK and c-MET (hepatocyte growth factor receptor, HGFR) and is currently being clinically investigated in several cancer indications." (PMID 33953226, 2021). "FAMC3 and MET copy numbers were investigated in various cancer samples and 200 cancer cell lines." (PMID 33596971, 2021). "However, given the cancer-intrinsic targets of Cabozantinib, both MET and AXL have been shown to participate in cell adhesion." (PMID 33041663, 2020). "In addition, both MET and AXL have been reported to be intrinsically linked to epithelial‐mesenchymal transition (EMT), promoting cell survival and cancer metastasis." (PMID 34766112, 2020). "TR1801‐ADC is highly active in MET‐amplified and cMet‐overexpressing cancer cell lines." (PMID 31736230, 2020). "A high-throughput secretome analysis has revealed that a shift from MET dependence to FGFR-2 and FGFR-3 dependence could lead to sustained cancer cell growth despite MET inhibition." (PMID 31963871, 2020). "In addition, we implemented the detection of MET expression in CTCs from cancer patients using two complementary technologies and obtaining promising results." (PMID 32102486, 2020). "One possible explanation may be that by the time the treatments are instituted in vivo, the cancer cells have already disseminated and HGF/c-MET inhibition by itself cannot exert any evident anti-cancer effects." (PMID 32203220, 2020). "A yet larger increase demonstrated the relative median fluorescence intensity increase (ΔMFI) suggesting that not only the proportion of MET/FLT4 bearing cells increase upon cancer development, but the intensity of cells’ expression (surface density) of these markers as well." (PMID 32899940, 2020). "Importantly, a significant correlation between cfDNA concentration and MET copy number (CN) in cancer patients (r = 0.57, p <10−10) was determined." (PMID 32102486, 2020). "In addition, CD105+/CD24− cancer stem cells of RCC also expressed MET, and inhibition reduced development of bone metastasis." (PMID 32290402, 2020). "Taken together, the role of HGF/MET in cancer seems to be quite complicated." (PMID 32435640, 2020). "Aberrant activation of MET is often detected in human cancers, and may result from different molecular mechanisms, such as genetic alterations, receptor overexpression, and autocrine stimulation." (PMID 32245152, 2020). "As there is some evidence of c-MET expressing dendritic cells targeting these cells may also provide another avenue via which c-MET inhibitors would be used to improve immunotherapy outcomes in cancer patients." (PMID 32117721, 2020).
cancer (continued). "With emerging evidence that c-MET may play a role in anti-cancer immune responses, understanding how c-MET may affect immunotherapy is another potential area to explore to see if these therapies could be used to greater effect." (PMID 32117721, 2020). "Here, we first tested the effects of MET on proliferation and viability of cancer cells." (PMID 33108409, 2020). "Overactivation of the c-MET/HGF system is a feature of many cancers." (PMID 33212946, 2020). "HGF/MET has oncogenic and pro-metastatic effects, but also has anti-cancer functions." (PMID 32435640, 2020). "c-MET induces cancer cell migration via the stimulation of cancer cell motility." (PMID 32825724, 2020). "Since miR-221 overexpression and MET pathway activation have been found in many cancers, the authors demonstrated that via both MET- and miR-221- knockdown, there is an increase in levels of tumor suppressor proteins, such as phosphatase and tensin homolog (PTEN)." (PMID 32717951, 2020). "Therefore, several clinical trials have assessed the efficacy of selective and broad-spectrum MET inhibitors in an extensive panel of cancers, generating interest in MET activity as a promising target for anticancer therapy." (PMID 32102486, 2020). "However, dysregulated overactivation of pro-HGF has been reported to aggressively induce cancer invasion and metastasis through increased phosphorylation of MET." (PMID 32290402, 2020). "The HGF/MET pathway is considered a promising target in multiple cancer types." (PMID 32435640, 2020). "At present, some non-specific inhibitors of MET tyrosine kinase such as crizotinib and cabozantinib have been approved for the treatment of other cancers, but all of the macromolecule or specific agents targeting HGFR/HGF are still at the clinical-trials stage." (PMID 32665850, 2020). "Moreover, analysis of scRNA-seq data reveals that MET is expressed in cancer cells and epithelial cells while RIPK2 is expressed in cancer cells, epithelial cells, monocytes, and neutrophils." (PMID 33204717, 2020). "Although the clinical application of ICIs is currently being expanded to a variety of malignancies, a combination of c-Met targeting therapies with ICIs should be considered in patients with MET-positive CTCs to improve the therapeutic efficacy of cancer immunotherapy." (PMID 33299117, 2020). "MET inhibitors could neutralize the activation of Janus kinases/STAT1 (signal transducers downstream of the IFNγ receptor) and counteract the induction of PD-1 ligands by IFNγ in MET-amplified cancers." (PMID 32435640, 2020). "According to the database of COSMIC, the world's largest and most comprehensive resource for exploring the somatic mutations in human cancer, chromosome 7 consists of lots of well-known cancer-related somatic mutations, including EGFR, BRAF, CDK6, MET, T1F1, and so on." (PMID 32695679, 2020). "MET protein overexpression and/or amplification are frequently found in different cancers." (PMID 32102486, 2020). "Among hundreds of thousands of signal receptors contributing to oncogenic activation, tumorigenesis, and metastasis, the hepatocyte growth factor (HGF) receptor – also called tyrosine kinase MET – is a promising target in cancer therapy as its axis is involved in several different cancer types." (PMID 32435640, 2020). "Several HGF/MET-neutralizing antibodies and MET kinase-specific small molecule inhibitors have been developed, resulting in some context-dependent progress in multiple cancer treatments." (PMID 32435640, 2020). "The role of HGF/MET signaling in the immune system in cancer is gaining attention since it could constitute a mechanism of primary and acquired resistance to cancer immunotherapy." (PMID 33276788, 2020).